MMP7 (matrix metallopeptidase 7)
Diseases named in the same sentence as MMP7 in open-access papers (continued):
Sharing a sentence is not in itself a finding about the gene and the disease.
tumor (continued). "Specifically, it has been reported that MMP-7 contributes to tumor invasion, proliferation, and antiapoptotic potential in CRC, while MMP-9 has been implicated in extracellular protein proteolysis during tumor invasion in CRC." (PMID 36901174, 2023). "In fact, MMP-7 has an approximately six-fold greater expression in tumor masses versus normal cells." (PMID 36831488, 2023). "In our study, analysis of tumour tissue gene expression indicated that MMP7 was expressed at higher levels in tumours of MIBC patients compared to NMIBC." (PMID 37391708, 2023). "Analysis of the microarray gene expression data from 213 NMIBC and 93 MIBC patient tumour biopsies revealed that MMP7 and MMP12 mRNA expression levels were higher in MIBC." (PMID 37391708, 2023). "Certainly, future modifications of NPs–EUG, such as replacement of casein with fibronectin, a known in vivo MMP-7 substrate, can open other administration routes besides IV, such as direct injection into the tumor mass under colonoscopy guides." (PMID 36831488, 2023). "For example, leptin stimulates the activation of MMP7 (Matrix Metallopeptidase 7), causing increased signaling of ERK (Extracellular Signal Regulated Protein Kinase) and JNK (c-Jun N-Terminal Kinase) pathways, resulting in tumor invasion." (PMID 37190027, 2023). "Both IgG1 and IgG4 are cleaved within the lower hinge by a number of inflammatory and/or tumor associated proteases -MMP-3 and MMP-12 at one site, Cathespin at a second site and by MMP-7/pepsin at a third site." (PMID 37713423, 2023). "MMP-7 promotes tumor progression by inhibiting apoptosis of cancer cells, reducing cell adhesion, and inducing angiogenesis." (PMID 36809261, 2023). "Based on the structure and composition of casein-coated NPs and the low level of MMP-7 in plasma compared to the tumor sites, the intravenous (IV) injection of NPs–EUG will be the first choice in the pre-clinical model." (PMID 36831488, 2023). "In summary, YEATS2 can affect tumor progression by regulating MMP7 expression through the PI3K/AKT signaling pathway." (PMID 36980736, 2023). "MMP7, a significant member of the MMPs family, has a function in tumor growth, metastasis, and angiogenesis." (PMID 37814323, 2023). "In contrast, MMP-7 expression is found to be higher in more aggressive forms of BC, correlates with tumor size, presence of metastasis to lymph nodes and distant metastasis." (PMID 37048701, 2023). "MMP7 is upregulated along the tumor-stroma boundary, consistent with its role in degrading extracellular matrix to facilitate tumor invasion." (PMID 37426750, 2023). "We further distinguished between tumour cells and non‐malignant epithelial cells using several marker genes, including MMP7, MMP9, MMP13 and HOXB2." (PMID 36588094, 2023). "A substantial body of evidence indicates that overexpression of MMP-7 plays an integral role in tumor pathogenesis and progression." (PMID 37513440, 2023). "The tumor-bearing mouse model demonstrates that inhibiting 5-LOX selectively reduces MMP-7 expression and the number of TAMs in tumor tissues." (PMID 37298230, 2023). "MMP-7 is abundantly expressed in numerous types of cancer tumor cells and overexpressed in precancerous cells and lesions." (PMID 36809261, 2023). "Previous research has demonstrated that MMP-7 promotes in vivo osteolysis and is differently expressed in the tumor-bone microenvironment in breast and prostate cancer." (PMID 37823051, 2023). "YAP1 is a protein that promotes transcription and MMP7 regulates and supports tumor proliferation and the inhibition of apoptosis." (PMID 36769287, 2023). "Our data also showed that increased levels of MMP7 were associated with VEGFA and were associated with tumor progression, metastasis, and immune invasion." (PMID 36672201, 2023). "MMP7 is highly expressed in many cancers, and its expression is related to survival time and tumor stage." (PMID 36936416, 2023).
tumor (continued). "Proinflammatory CD80, CXCL10, anti‐inflammatory IL‐10, and the tumor‐associated markers MMP2, MMP7, MMP12, and MGLL showed lower baseline expression and were upregulated in macrophages as well." (PMID 38037545, 2023). "MMP7 is found to be involved in tumour invasion, metastasis, angiogenesis and inflammatory processes." (PMID 38131168, 2023). "The overall development depends on the expression of EMT proteins “gastrin and matrix metalloproteinase-7 (MMP-7)”; MMP-7 is responsible for cleaving superficial proteins, promoting cancer cell linkage, and strengthening tumor metastasis." (PMID 37609398, 2023). "In the present study, we aimed at understanding the cross‐talk between acquired drug resistance and tumor progression, linking MMP7 and Hsp90." (PMID 32761892, 2022). "By eliminating cell apoptosis, MMP-7 reduces the effect of chemotherapy even promoting tumor growth." (PMID 36776395, 2022). "The diverse cells composing tumor stroma secrete specifically the different MMPs; however, many tumor cells express MMP7, apparently in parallel with the implementation of EMT program." (PMID 35789101, 2022). "Histological and molecular analyses suggest a focal distribution of MMP-7 with an accentuated expression at the invasive tumour front, suggesting its involvement in tumour infiltration." (PMID 35327500, 2022). "While studying the effects of Hsp90 inhibition against the drug‐resistant tumor cells, we have come across MMP7 interference with the therapeutic response mediated by Hsp90 inhibitor, 17AAG." (PMID 32761892, 2022). "PKP3 plays some roles in the tumor microenvironment, such as regulating cell invasion and tumor formation via MMP7 proteins and regulating adhering junctions and mesenchymal-epithelial transitions by interaction with desmoglein and desmocollin." (PMID 35075375, 2022). "We demonstrated that MMP7 facilitates both drug efflux activity and metastasis of tumor cells, however, in coordination with the cancer chaperone Hsp90." (PMID 32761892, 2022). "Our data demonstrated that hAFMSCs strongly inhibit PDAC cell proliferation, tumor growth and invasion, possibly by altering cell cycle arrest and MMP7 signaling-triggered EMT." (PMID 35659367, 2022). "MMP7 plays a crucial role in the tumor cell invasion cascade and migration through the activation of β-catenin signaling." (PMID 35659367, 2022). "The KB cells exhibited tube formation on 3D culture conditions, whereas MMP7 OE has increased the number of branch points indicative of the enhanced angiogenic potential of tumor cells." (PMID 32761892, 2022). "Our results demonstrate that MMP7 can influence the homing properties of tumor cells, and 17AAG treatment inhibits." (PMID 32761892, 2022). "The Wnt and STAT3 pathways can be involved in the regulation of MMP-7 expression, suggesting that host cellular effectors produced in the tumor microenvironment start playing an important role in MMPs regulation." (PMID 35163805, 2022). "MMP7 expression was also found to be positively correlated with infiltration of dendritic cells and macrophages in some specific tumor types." (PMID 35785154, 2022). "MMP7 can be considered a biomarker in tumors of the digestive tract like colon, pancreas, or gastric cancer." (PMID 35789101, 2022). "For instance, MMP7 has been widely reported to promote tumor angiogenesis by transforming the extracellular matrix, thereby participating in the invasion and metastasis of ccRCC." (PMID 36353536, 2022). "GAD1 has been reported to stimulate tumor cell invasion and metastasis by regulating β-catenin translocation and activating MMP7." (PMID 36671437, 2022). "MMP7 promotes tumor cell invasion and migration, digesting the extracellular matrix (ECM) and components of cell surface proteins." (PMID 36009404, 2022).
tumor (continued). "By translating our in vitro findings in vivo, we display that Hsp90 links MMP7 with the drug efflux activity, thus adds to the list of molecules to be considered for treating the drug adapted metastatic tumor cells." (PMID 32761892, 2022). "Immunostaining showed lower protein expression of Wnt7a, Wnt7b, Mmp7 and Ccnd2 in tumor tissues of the PRDX6 knockout group compared to the wild-type group." (PMID 36209344, 2022). "Our results showed that RAB26 silence reduced the expression of Ki67, PCNA, MMP2 and MMP7 in xenograft tumor samples, suggesting the suppression of RAB26 silence on NSCLC growth and metastasis in vivo." (PMID 35291909, 2022). "Further, an over-expression of MMP-7 was detected in all tumor samples as confirmed also by individual and mean densitometric values of tumor vs. normal skin samples, and the difference between the two groups was statistically significant (t-test; P < 0.05)." (PMID 36518899, 2022). "Our results also showed that the expression level of MMP7 in tumor samples was highly heterogeneous, and its expression level associated with resistance to Sorafenib." (PMID 36064367, 2022). "We demonstrated a cross‐talk between Hsp90 and MMP7 in regulating the acquired drug resistance and tumor progression." (PMID 32761892, 2022). "While 17AAG treatment of Parental cells restricted tumor metastasis to spleen, 17AAG treatment of MMP7 OE cells completely inhibited the tumor metastasis." (PMID 32761892, 2022). "On the contrary, Kaiso has also been suggested to be a potential tumour suppressor, which repressed the transcription of MMP7, CCND1 and WNT11 genes involved in oncogenesis and metastasis." (PMID 35851744, 2022). "MMP-7 expression occurs mainly in tumor cells, and it promotes tumor progression by facilitating ECM turnover and remodeling, decreasing cell adhesion and inflammation, enhancing cell proliferation, inhibiting apoptosis, and inducing angiogenesis." (PMID 35496040, 2022). "Further studies showed that osteoclast-derived MMP-7 significantly contributed to tumor growth and tumor-induced osteolysis." (PMID 36497209, 2022). "The Parental and MMP7 OE cells were injected subcutaneously into the pelvic region of male nude mice were monitored for 6 weeks for the localized subcutaneous (s.c.)tumor growth." (PMID 32761892, 2022). "We recently assessed MMP-7 levels in serum samples of a largely overlapping UTUC cohort and found higher MMP-7 levels to be associated with higher tumor stages and the presence of metastasis." (PMID 36289821, 2022). "Despite cells exhibiting increase invasion and migration, we observed decreased s.c. tumor volume in response to MMP7 OE, suggesting the possibility of tumor invasion." (PMID 32761892, 2022). "The protein expression of RAB26, Ki67, PCNA as well as MMP2 and MMP7 in xenograft tumor tissues from each group was also determined by western blot assay." (PMID 35291909, 2022). "M2 macrophages secrete many factors, such as, IL-6, IL-8, IL-10, TGF-β, PGE2 and MMP7, and these macrophages promote immunosuppression and tumor growth." (PMID 36059695, 2022). "The expression of MMP7 was significantly higher in STAD tumor tissue when compared with the para-cancerous tissue (P < 0.01), findings that are consistent with online data from TCGA and CPTAC datasets." (PMID 35785154, 2022). "After the transferase up-regulated MMP-7, tumor invasion and metastasis proceeded more rapidly and smoothly." (PMID 36119495, 2022). "In CRC samples, immunostaining for MMP-7, MMP-14 and TIMP-1 were localized primarily in tumor cells, but also in stromal cells (cancer-associated fibroblasts (CAF) as well as MICs)." (PMID 33946534, 2021). "MMP2 and MMP7 belong to the family of zinc-dependent endopeptidases, which play a fundamental role in tumor invasion and metastasis." (PMID 33833997, 2021).
tumor (continued). "For example, animal experiments showed that treating mice with JNK- or ERK-specific inhibitors decreased MMP-7 expression in tumor tissue, suggesting that MMP-7 induction occurs via the activation of JNK and ERK." (PMID 34769248, 2021). "Consistently, compared to the low-MMP7 patients, patients with high MMP7 showed larger tumor size (χ2 = 7.013, P = 0.008), more depth of tumor invasion (χ2 = 5.979, P = 0.014) and more advanced TNM stage (χ2 = 5.961, P = 0.015)." (PMID 34215253, 2021). "MMP-7 can also degrade the Fas ligand on the cell membrane, inhibit Fas-mediated apoptosis, and promote tumor growth." (PMID 34485109, 2021). "After treatment with hsBCL9CT-24, MMP7, one of the Wnt/β-catenin signaling pathway targets, was significantly downregulated in tumor cells, as expected." (PMID 34790117, 2021). "These nodes include the machinery for ACh production in the tumor microenvironment, selective inhibitors of M3R activation and MMPs, like MMP7 which mediates release of HB-EGF and activation of EGFR, and a host of key downstream signaling molecules." (PMID 33450835, 2021). "Exogenous overexpression of MMP7 promoted T-DM1 resistance and tumor growth, while MMP7 knockdown was associated with the opposite phenotype." (PMID 34485109, 2021). "MMP-7 has been shown to accord protection to tumor cells from apoptosis via stabilization of major extrinsic death pathway receptor and ligand duo Fas, as well as Fas-L." (PMID 33918254, 2021). "The function of MMP7 usually complements the classical tumor properties, leading to invasion, immune immunity, and metastasis of tumor cells and plays an important role in the carcinogenesis process." (PMID 34621293, 2021). "MMPs (MMP7 and 9) along with collagen proteins were found to be important for tumour vascular invasion." (PMID 34824625, 2021). "The dynamic interaction between MMP-7 and perlecan in metastatic PCa cells is a key regulator of cell behavior in the tumor microenvironment." (PMID 33809984, 2021). "These analyses revealed protein expression of Paneth cell markers Lysozyme and MMP7 in IDO1+ tumor cells." (PMID 32444775, 2020). "Several studies have indicated that EGCG appeared to be an inhibitor of cancer cell metastasis via an increase in the expression of E-cadherin and inhibition of the expression of N-cadherin, Zeb-1, MMP-2, and MMP-7 in tumor tissues." (PMID 33113766, 2020). "And only a weak correlation between the serum level of MMP7 and the tumour tissue level of MMP7 has been reported in GC." (PMID 33005257, 2020). "As known to us, MMP-7 is a member of the proteolytic enzyme family, which promotes the invasion and metastasis of tumor cells by degrading the basement membrane and extracellular matrix." (PMID 32851100, 2020). "The effect of MMP7 on lymph node metastasis in vivo was analyzed using a high-metastasis orthotopic nude mouse tongue transplanted tumour model." (PMID 31937294, 2020). "Few papers have reported on MMP7 as a tumour regulator in TSCC, although its function in facilitating tumourigenesis is canonical in many cancers." (PMID 31937294, 2020). "The results showed that age group, T stage, N stage, chemotherapy, and coexpression of MMP-7 and TIMP-1 in tumour tissues were associated with patient survival." (PMID 33005257, 2020). "We also discovered that ECM substrates of MMP24 and MMP7 are different and that MMP7 expression promotes angiogenesis, which has a central role in tumor growth and metastasis, whereas the role of MMP24 in angiogenesis has not been clarified." (PMID 32093160, 2020). "Tissue MMP-7 levels were analyzed by immunohistochemistry in 72 formalin-fixed, paraffin-embedded chemo-naïve tumor samples, while MMP-7 serum concentrations were determined in 132 serum samples of an independent cohort of 52 patients." (PMID 33396213, 2020). "We next examined the relationship between MMP24 and MMP7 expression with respect to tumor aggressiveness." (PMID 32093160, 2020).
tumor (continued). "Accordingly, a growing body of evidence supported that MMP-7 is involved in platinum resistance by allowing tumor cells to escape from chemotherapy-induced apoptosis." (PMID 33396213, 2020). "According to the available data, MMP-2 and MMP-7 are among the most important metalloproteinases in the pathogenesis of tumor formation." (PMID 32751899, 2020). "The dominant-negative effect of CD95L binding-deficient CD95 variants is possibly also of relevance in tumor development as it has been observed that MMP-7 cleaves off a part of the CD95 PLAD resulting in reduced apoptosis sensitivity of tumor cells." (PMID 33644033, 2020). "Furthermore, many authors have proposed that MMP7 may indirectly destroy the vital components of the extracellular matrix by activating other individual MMPs or associating with other MMPs to promote tumour cell metastasis." (PMID 31937294, 2020). "A study investigating the serum levels of TIMP-1 and MMP-7 in patients with metastatic CRC found that serum MMP-7 together with TIMP-1 can be used as effective tumour markers for detecting metastatic CRC." (PMID 33005257, 2020). "TAMs have also been associated with increased matrix metalloproteinase-7 (MMP-7) expression in hypoxic regions of the TME; MMP-7 inhibits tumor cell lysis via cleavage of the Fas ligand, a transmembrane protein involved in apoptosis." (PMID 33348579, 2020). "It has been reported that MMP7 is one of the most important MMPs in colorectal tumorigenesis, promoting angiogenesis, invasiveness, and tumor survival." (PMID 32410997, 2020). "MMP-7 staining showed a diffuse, fine granular pattern and was predominantly localized in the cytoplasm of tumor cells." (PMID 33396213, 2020). "On the one hand, expression of MMP-7 gradually increases with tumour progression, and eventually, highly expressed MMP-7 induces expression of TIMP-1 to regulate proteinase reactions." (PMID 33005257, 2020). "APC mutation promotes CRC initiation through the activation of β-catenin and transcription-factor-4 (TCF4) complex which targets tumor progression-promoting genes, such as Myc, cyclin D1, and matrix metallopeptidase 7 (MMP7)." (PMID 33271948, 2020). "Associations between coexpression of MMP-7 and TIMP-1 in tumour tissues and the survival of GC patients were evaluated by a stratified analysis of age group, T stage, N stage, and chemotherapy." (PMID 33005257, 2020). "The MMP7 gene plays a significant role in tumor cell invasion and metastasis due to its ability to degrade components of the extracellular matrix (ECM) and basement membrane (BM)." (PMID 30940992, 2019). "The results above further convinced us that GP73 modulated trafficking of intracellular MMP-7 in tumor-related tissues." (PMID 31591387, 2019). "The levels and co-localization of GP73 and MMP-7 in primary tumor tissues and adjacent liver tissues (n = 90) were further examined using immunofluorescence staining." (PMID 31591387, 2019). "SR9243 also upregulated or downregulated genes associated with tumour proliferation, apoptosis, angiogenesis, invasion and migration, such as ANGPTL4, PDGFR, DUSP5, MMP7, FOXQ1 and MXD1 26–31." (PMID 31138790, 2019). "Compare bilateral neoplasm subdivision group to one side neoplasm subdivision group, only levels of MMP-7 and MMP-9 showed significant differences (p < 0.05)." (PMID 31406154, 2019). "MMP7 is one of the most important β-catenin-targeted genes, and plays a crucial role in tumor cell migration and invasion." (PMID 31766223, 2019). "Specific molecules which have the role of degrading proteins are called matrix metalloproteinases and are released in the tumor environment by tumor cells (MMP7, 14, 15, and 16), inflammatory cells (MMP12), and fibroblasts (MMP1, 2, 3, and 13)." (PMID 31934531, 2019). "The expression level of MMP-7 at the invasive front of the tumour is relatively higher than the core, which indicates that the upregulation of MMP-7 is associated with cancer aggressiveness in GC." (PMID 29795331, 2018).